IL2 (interleukin 2)
Diseases named in the same sentence as IL2 in open-access papers (continued):
Sharing a sentence is not in itself a finding about the gene and the disease.
periodontitis (continued). "Interestingly, maximal expression of Treg-related genes Foxp3, IL-2, IL-10, CTLA-4, CD25, and GITR was reached later than Th17-related genes, on day 15 post-periodontitis induction." (PMID 33149125, 2020). "In contrast, in the present series, we observed that other ratios, such as IL1beta/IFNgamma, ILbeta/IL2, ILbeta/IL3 and ILbeta/IL4, may play an essential role in quantitative terms in chronic periodontitis." (PMID 30573746, 2018). "Only CD274 (programed death-ligand 1 with a major role in suppressing the immune system through a signal that inhibits TCR-mediated activation of IL-2 production and T cell proliferation) and ID3 (DNA-binding protein inhibitor ID-3 is a transcription inhibitor) were decreased with periodontitis." (PMID 27486459, 2016). "Periodontitis patients have significantly elevated levels of LY96, which leads to the formation of LY96-TLR4-CD14 complexes that trigger the myeloid differentiation factor-88 (MyD88) pathway, resulting in TNF-α, IL-6, IL-8, and IL-2 production in the gingival tissue." (PMID 39555084, 2024). "The polymorphisms of IL-2 and TNF-α of Th1 cytokine family may be associated with the pathogenesis or the prevention of periodontitis risk, while the polymorphism of IFN-γ is not related to periodontitis risk." (PMID 35046930, 2021). "The present meta-analysis showed that the polymorphisms of the members IL-2 and TNF-α of Th1 cytokine family may be associated with the pathogenesis of periodontitis or the prevention of periodontitis risk, while the polymorphism of IFN-γ is not related to periodontitis risk." (PMID 35046930, 2021). "The levels of IL-2, IL-6 and IFN-γ were increased in saliva from RA patients compared to control subjects, both without periodontitis (P < 0.05)." (PMID 31182740, 2019). "IL-2, IFN-γ, TNF and IL-33 exhibited an approximately two-fold increase in RA subjects without periodontitis compared to matched controls." (PMID 31182740, 2019).
sarcoma (40 papers, 2011 to 2025). A usually aggressive malignant neoplasm of the soft tissue or bone. "In a phase I clinical trial with sarcoma patients, NK-92 therapy was found safe but ineffective, possibly be due to IL-2 dependency of NK-92 cells and associated poor in vivo persistence." (PMID 33322371, 2020). "This hypothesis is supported by a study in cats with vaccine-associated sarcomas which reported decreased tumor recurrence in patients treated post-operatively with recombinant poxvirus expressing interleukin-2." (PMID 30060548, 2018). "Small studies in sarcoma have shown IL-2, even conjunction with LAK cells or IFNs, offers limited antitumor effects." (PMID 40469285, 2025). "Localized delivery strategies, including nebulized liposomal IL-2 in canine pulmonary metastases and intrathoracic administration in murine sarcoma models, reduce systemic toxicity while promoting immune activation and tumor regression." (PMID 40143046, 2025). "Another study in relapsed pediatric sarcoma patients found that high‐dose IL‐2 therapy elicited complete responses in two of four osteosarcoma cases." (PMID 33152115, 2021). "An animal sarcoma model studied the effect of radiotherapy (RT) on ex vivo IL-2 preactivated and reinfused NK cells." (PMID 33498238, 2021). "In another preclinical model of pediatric sarcoma, the combination of oncolytic measles vaccine virotherapeutics together with IL-2 preactivated human NK cells resulted in an increased release of granzymes, perforin, and granulysin from NK cells." (PMID 33498238, 2021). "IFN-γ-treated MCA sarcomas with initially high levels of H60 were resistant to killing by IL-2-activated NK cells." (PMID 33322371, 2020). "Addition of PBMC stimulated with IL-2 or addition of NK cells resulted in an even higher cytotoxicity on the addressed sarcoma cells, whereby the cytotoxic effect again was significantly stronger on MeV-infected A673 cells than on mock-infected cells." (PMID 31795974, 2019). "A variety of immunomodulatory agents have been investigated for the treatment of sarcomas, including cytokines such as interleukin-2 (IL-2) and IFN." (PMID 26301204, 2015). "As expected, the presence of interleukin 2 increased the number of cells that reacted with the sarcoma cells." (PMID 26579494, 2015). "Interleukin-2 (IL-2) and interferons (IFNs) have been used in the immunotherapy for sarcomas, and clinical results are evident." (PMID 26167500, 2015). "The 4 highest IL-2 secretor clones identified in this initial screen were then selected for further analysis and cultured with anti-c-myc antibody or the sarcoma cell line 24JK transfected to express erbB2 or controls, and IL-2 secretion determined." (PMID 23667569, 2013). "In vitro culture of T cells with IL-2 and sarcoma antigen resulted in significant enhancement in cytotoxic efficacy." (PMID 23326300, 2013). "Nevertheless, IL-2-induced immune activation suggests potential efficacy for a subset of sarcoma." (PMID 40469285, 2025). "As early as 1997, studies showed that IL-2(+) and CD80(+) tumor vaccines could protect and prolong the survival time of a higher proportion of sarcoma-bearing mice compared with IL-2(+) tumor vaccines." (PMID 39575257, 2024). "In this paper, we present an open-label, non-randomized, non-comparative pilot study of bempegaldesleukin, a CD122-preferential interleukin-2 pathway agonist, with nivolumab in refractory sarcoma at Memorial Sloan Kettering/MD Anderson Cancer Centers (NCT03282344)." (PMID 35710741, 2022). "Only a few clinical trials of IL-2 for sarcomas have been reported." (PMID 30693030, 2019). "The responses observed with IL-2 suggest that this agent may have efficacy in a subset of patients with sarcoma." (PMID 24778572, 2014). "In a sarcoma model using anti-CD3 activated TDLN, CD8 cells caused tumor regression while CD4 cells did not result in tumor regression but instead provided a helper function to CD8 cells that could be replaced with exogenous IL-2." (PMID 26090481, 2015).
sarcoma (continued). "In mice with MCA-106 sarcoma lung metastases (C57BL/6 strain), administering IL-2 liposomes via intrathoracic delivery enhanced survival and demonstrated antitumor effects." (PMID 40143046, 2025). "In a two-tumor sarcoma mouse model, where only one of the two tumors received irradiation, anti-PD1 was added to the combination of RT and IL-2c (complex, IL-2/anti-IL-2)." (PMID 39218928, 2024). "Finally, TIL therapy is under early investigation in sarcomas; in this modality, autologous TILs are collected from an individual patient’s tumor and then expanded, and then returned to the patient with lymphodepleting chemotherapy and interleukin-2 (IL-2) therapy." (PMID 35582530, 2022). "First, obvious clinical effects have been achieved with cytokines, including interleukin-2 (IL-2) and interferon (IFN), used for sarcoma immunotherapy." (PMID 34079754, 2021). "As mice experiments have previously shown, the combination of IL-2 and β-cyclodextrin-benzoic acid enables to improve the LAK killer activity towards sarcoma cells." (PMID 22084730, 2011). "An ongoing clinical trial (NCT03935893) is studying adoptive transfer of TILs for advanced solid tumors including sarcoma, and another (NCT04052334) is evaluating the safety and feasibility of TIL treatment with high-dose IL-2 in patients with soft tissue sarcoma." (PMID 40145091, 2025). "In addition, DFMO and GC7 treatment sustained CD69 expression in CD8+ T cells from human sarcoma tumor infiltrating lymphocytes (TIL) following activation with anti-CD3/CD28 and IL-2." (PMID 37581943, 2023). "Here, the authors report the results of a pilot clinical trial to assess the efficacy and safety of bempegaldesleukin, a CD122-preferential interleukin-2 (IL-2) pathway agonist, in combination with the PD1 blockade (nivolumab) in patients with locally advanced or metastatic high-grade sarcoma." (PMID 35710741, 2022). "Alternatively, when glycolysis was inhibited in CD8+ T cell using 2-deoxy-D-glucose (2-DG) in the mouse sarcoma model, interferon gamma (IFNγ) but not Interleukin-2 (IL-2) production was inhibited." (PMID 34268109, 2021). "Thus, combinatorial treatment of A673 sarcoma cells with oncolytic virus MeV-GFP and PBMCs stimulated with IL-2 or with NK cells was found to be highly superior when compared with the respective monotherapies." (PMID 31795974, 2019). "The future of IL-2 as a single agent for the treatment of sarcoma patients is not known; there is, however, a study combining IL-2 with vaccine therapy (NCT00101309)." (PMID 24778572, 2014). "Though few cytokine and growth factor studies have been conducted on sarcomas, some research has documented elevated serum levels of VEGF, IL-2 and bFGF in sera of patients with soft tissue sarcomas; VEGF serum levels correlated significantly with tumor size and histological grade." (PMID 24085323, 2013). "To determine whether our findings were relevant in the context of non-TCR transgenic T cells, we evaluated the role of IL-2 in the acquisition of cytotoxic activity by CD4+ T cells in MCA205 sarcoma, which is known to respond to αCTLA-4 monotherapy." (PMID 31924474, 2020). "The use of IL-2 as sole adjuvant agent after sarcoma resection is not warranted at the moment." (PMID 23927575, 2013). "In a small study of high dose IL-2 used in conjunction with LAK cells, none of the six sarcoma patients treated responded." (PMID 24778572, 2014).
acute respiratory distress syndrome (37 papers, 2013 to 2026). Progressive and life-threatening pulmonary distress in the absence of an underlying pulmonary condition, usually following major trauma or surgery. "The viral entry initiates a cascade of events that includes the infiltration of proinflammatory markers, such as interleukin-2, interleukin-6, and tumor necrosis factor-alpha, leading to the development of acute respiratory distress syndrome." (PMID 40621321, 2025). "Pro-inflammatory interleukins like IL-1β, IL-6, IL-2, IL-17 and IL-18 are critically involved in cytokine storm, hyperinflammation, and acute respiratory distress syndrome, whereas anti-inflammatory cytokines like IL-10 contribute to immune regulation and resolution of inflammation." (PMID 41683812, 2026). "Increased proinflammatory cytokines such as IL-1, IL-2, IL-6, IL-7, IL-10, are frequently observed in many COVID-19 patients, which is closely related to the acute respiratory distress syndrome (ARDS), multiorgan failure and other severe symptoms." (PMID 37228604, 2023). "In the context of SARS-CoV-2, a phase 2 clinical trial has been completed looking at the efficacy of low-dose IL-2 in acute respiratory distress syndrome (ARDS) related to COVID-19 (NCT04357444)." (PMID 37928543, 2023). "Massive systemic release of pro-inflammatory mediators such as interleukin (IL)-1β, IL-2, IL-6, IL-7, IL-10, tumor necrosis factor-α (TNFα), granulocyte colony-stimulating factor (G-CSF), etc., also known as cytokine storm, contributes to the acute respiratory distress syndrome (ARDS)." (PMID 35888733, 2022). "The cytokine storm phenomenon is an increase in pro-inflammatory cytokine levels in the serum, such as IL-2, IL-6 and IL-1β, IL-17, IL-8, G-CSF, GM-CSF, IP10, MCP1, MIP1α (also known as CCL3), and TNF, and causes acute respiratory distress syndrome (ARDS) in severe COVID-19 cases." (PMID 37626992, 2023). "This cytokine storm is characterized by elevated plasma concentrations of IL-2, IL-7, IL-10, GCSF, IP-10, MCP-1, MIP-1A and TNF-α, and contributes to the development of acute respiratory distress syndrome (ARDS)." (PMID 34208037, 2021). "This exaggerated response leads to the production of a number of pro-inflammatory cytokines including IL-1β, IL-2, IL-6, IFN-γ, and TNF-α, which can lead to endothelial cell injury, acute lung injury (ALI), acute respiratory distress syndrome (ARDS), and vascular collapse (shock)." (PMID 24141285, 2013). "This patient experienced progressive signs of an acute respiratory distress syndrome (ARDS) resulting in respiratory failure and need of invasive respiratory support shortly after TIL infusion and the first IL-2 dose." (PMID 39801681, 2024). "Elevated early pro-inflammatory cytokines like interleukins (IL2, IL6, and IL10) and Tumor necrosis factor (TNF) in ICU subjects reflect the cytokine storm leading to acute respiratory distress syndrome (ARDS) and progressive multiple organ failure." (PMID 33869282, 2021). "The overexpression of cytokines such as IL-2, IL-6, IL-7, GSCF, IP10, MCP1, MIP1A, and TNFα is followed by edema, which impairs oxygen exchange, and may lead to acute respiratory distress syndrome (ARDS) causing potential acute cardiac injury, secondary infection, and death." (PMID 32574317, 2020). "Similarly, in a mouse model of acute respiratory distress syndrome (ARDS), treatment with THC led to a 100% survival rate, a reduction in the infiltration of immune cells into the lungs, and a reduction in the proinflammatory cytokines IFN-γ, IL-1β, IL-2, IL-6, and TNF-α." (PMID 38202234, 2023).
Anxiety (36 papers, 2007 to 2026). Intense feelings of nervousness, tension, or panic often arise in response to interpersonal stresses. "IL-2, which has been linked to anxiety in this instance, affects the way the brain’s HPA axis functions, as well as how different neurotransmitters are modulated." (PMID 39768715, 2024). "Our results showed that IL‐2 was negatively associated with anxiety symptoms and positively correlated with cognitive impairment." (PMID 32790154, 2020). "IL-2 has been shown to impair synaptic plasticity and cause neuroinflammation, which ultimately leads to neuronal damage in neurocircuits associated with fear and anxiety signal transduction." (PMID 38902708, 2024). "The increases in IL-2 that we observed might predict more post-concussion symptoms after the acute phase and may predict an associated anxiety-like state." (PMID 37628746, 2023). "Second, in the HA rats, liver damage and anxiety were associated with an imbalance between GCs and cytokines that expressed in the decrease of blood Cort with a simultaneous increase of IL-1 and IL-2 and with a decrease of IL-4 and IL-10 concentrations in the blood and in the liver." (PMID 37629192, 2023). "Limited evidence suggests that high levels of pro-inflammatory markers, such as IL-2, correlate with high scores on anxiety tests in MS patients." (PMID 39768715, 2024). "There are studies that support our findings that in some animal models and clinical trials, the higher the level of IL‐2, the lower the level of anxiety." (PMID 32790154, 2020). "On the other hand, mRNA levels of IL-2 were reported to decrease in the PFC under increased anxiety in the elevated plus maze (EPM) test." (PMID 29849816, 2018). "After chronic dioscorea treatment, a decrease in anxiety and IL-2 levels was observed in the HA OVX rats." (PMID 17688703, 2007). "As the amygdala is correlated with the pathophysiology of anxiety, the function of IL-2 in this area deserves further study." (PMID 17688703, 2007). "The present results provide a new insight into the pathophysiological role of IL-2 in postmenopausal anxiety." (PMID 17688703, 2007). "The lack of a significant association between IL-2 serum levels and anxiety severity highlights the nuanced nature of immune dysregulation in GAD, warranting further exploration into the specific mechanisms involved." (PMID 38902708, 2024). "DHA and EPA may suppress the release of inflammatory cytokines, including TNF-α, Interleukin 1 (IL-1), IL-2, and IL-6, which may have an anti-anxiety or anti-depressive effect." (PMID 38979505, 2024). "Interestingly, many studies support the results that IL‐2 is positively correlated with anxiety (Mann, Dail, & Bailey, 2016)." (PMID 32790154, 2020). "Indeed, we observed an effect of rearing in female anxiety-like behavior and functional connectivity after the age when innervation to the PL and IL2 was increased (PD28)." (PMID 31958061, 2020). "The present data suggest that IL-2 in the brain could play a role in postmenopausal anxiety and could be involved in the mechanisms by which dioscorea decreases anxiety levels in HA OVX rats." (PMID 17688703, 2007). "In addition, IL-2/15Rβ knockout mice exhibit decreased levels of anxiety behavior in the EPM test compared to wild-type and heterozygote mice." (PMID 17688703, 2007). "In addition, IL-2/15Rβ knockout mice exhibit decreased levels of anxiety-like behaviour in the EPM test compared to wild-type and heterozygote mice." (PMID 17688703, 2007). "Anxiety levels in rats are correlated with interleukin-2 (IL-2) levels in the brain." (PMID 17688703, 2007). "Notably, HSP resulted in a significant attenuation of anxiety- and depression-associated behaviors, a reduction in pro-inflammatory cytokine levels (TNF-α, IFN-γ, IL-1β, IL-2, IL-6), and an augmentation of neurotrophic factors (NT-3, BDNF, NGF) within the striatum." (PMID 41346684, 2025).
Anxiety (continued). "In addition, there is evidence that IL-2-induced neurochemical changes might have a delayed functional relevance for affective conditions, such as anxiety-like behaviour." (PMID 23536796, 2013). "We evaluated the association of putative functional and tag SNPs within IL1B, IL2, and IL6 with aggression case status, parent‐reported internalizing problems, self‐reported anxiety symptoms, and self‐reported depressive symptoms in our sample." (PMID 36168941, 2022). "Furthermore, the effects of dioscorea on behavior and IL-2 levels were dependent on the anxiety levels of the OVX rats and had task-dependent behavioral consequences, indicating that cytokine responses to treatment might be involved in the individual differences in anxiety levels." (PMID 17688703, 2007).